NUSAP1 (nucleolar and spindle associated protein 1)
Diseases named in the same sentence as NUSAP1 in open-access papers (continued):
Sharing a sentence is not in itself a finding about the gene and the disease.
pancreatic cancer (14 papers, 2015 to 2025). "In pancreatic cancer, nucleolar and spindle-associated protein 1 (NUSAP1) has been found to form a transcriptional regulatory complex with c-MYC and HIF-1α." (PMID 41007358, 2025). "There are only a few reports on the role of NUSAP1 in the occurrence and progression of pancreatic cancer." (PMID 38229038, 2024). "The biological function of ECT2 in pancreatic cancer had been discussed in our previous work, so we mainly focused on NUSAP1 during subsequent research." (PMID 35483343, 2022). "In our study, we found that NUSAP1 is highly expressed in pancreatic cancer, which is an indicator of poor prognosis." (PMID 35483343, 2022). "Although, one study has found that hypoxic stress stimulates the rapid translation of NUSAP1 in pancreatic cancer cells." (PMID 34322597, 2021). "Using these approaches, we found that overall survival was the main clinical trait associated with the transcriptome profiles of pancreatic cancer patients, and that DSG3, ARNTL2, NUSAP1 and KRT7 were independent prognostic factors." (PMID 32081836, 2020). "Our prognostic model containing four DEGs (DSG3, ARNTL2, NUSAP1 and KRT7) was used to determine the risk scores of pancreatic cancer patients, and patients with high risk scores were found to exhibit poor overall survival." (PMID 32081836, 2020). "Promotion of pancreatic cancer cell invasion through the microRNA-569/NUSAP1/ZEB1 axis." (PMID 40535133, 2025). "In a pancreatic cancer study, Liang found that the Kla modification of nucleolar and spindle-associated protein 1 (NUSAP1) regulates LDHA expression, establishing a positive feedback loop involving NUSAP1 Kla, LDHA, glycolysis, and lactate." (PMID 40755753, 2025). "Furthermore, one study has shown that hypoxia stimulates the rapid translation of NUSAP1 in pancreatic cancer cells." (PMID 34322597, 2021). "This study provides a comprehensive analysis of the regulatory features and detailed mechanisms governing NUSAP1 throughout the mitotic cell cycle, along with its influence on the initiation and progression of digestive system cancers, including liver, gastric, esophageal, and pancreatic cancer." (PMID 40535133, 2025). "Lactate-induced lactylation inhibits the degradation of NUSAP1, forming a positive feedback loop of NUSAP1-LDHA-glycolysis-lactate, which promotes pancreatic cancer metastasis and negatively affects the prognosis of pancreatic cancer." (PMID 41007358, 2025). "Our data concluded: miRNA-569 modulates the NUSAP1/ZEB1 signaling axis, exert anti-tumor function, which is expected to be the clinical therapeutic target of pancreatic cancer." (PMID 35483343, 2022). "The role of CRABP2 and NUSAP1 in pancreatic cancer is currently unclear, but CRABP2 and NUSAP1 favors proliferation and invasion of several types of tumor, such as prostate, lung, gastric and colorectal cancer." (PMID 33748143, 2021). "Based on the transcriptomics profiling of anlotinib in this work and available pancreatic cancer related data deposited in TCGA, GEO, and ICGC databases, we further constructed a prognostic model which consists of five crucial genes, namely TOP2A, CRABP2, CDK1, NUSAP1, and PERP." (PMID 33748143, 2021).
liver cancer (13 papers, 2019 to 2025). An epithelial or non-epithelial malignant neoplasm that arises from the liver. "NUSAP1 was not only up-regulated in NAFLD liver cancer but also associated with shorter OS (p < 0.05), RFS (p < 0.05), PFS (p < 0.05) and DFS (p < 0.05)." (PMID 35431924, 2022). "In patients with liver cancer, the level of NUSAP1 expression is closely associated with the severity of the prognosis, whereas interference with NUSAP1 expression inhibits the growth of liver cancer cells." (PMID 32420375, 2020). "E2F8 enhances cisplatin resistance in liver cancer cells by activating NUSAP1, which in turn inhibits DNA damage." (PMID 40535133, 2025). "Prior studies revealed that a variety of tumors, including liver cancer, have aberrantly high levels of NUSAP1." (PMID 39911278, 2025). "By decreasing apoptosis and accelerating cell cycle progression, NuSAP1 aided in the growth of liver cancer." (PMID 39911278, 2025). "Conversely, silencing NUSAP1 results in cell cycle arrest in liver cancer cells increases DNA damage, and sensitizes these cells to cisplatin-based chemotherapy." (PMID 40535133, 2025). "E2F8 transcriptionally activates the target gene NUSAP1, thereby alleviating DNA damage and mediating cisplatin resistance in liver cancer cells." (PMID 40535133, 2025). "Follow-up studies revealed that HBx-induced upregulation of NUSAP1 significantly enhanced liver cancer cell proliferation in both experimental and physiological settings, thereby promoting hepatocarcinogenesis." (PMID 40535133, 2025). "NUSAP1 serves as a poor prognostic indicator for liver cancers, and potentially plays a crucial role in HBV-HCC progression by promoting proliferation and inhibiting apoptosis." (PMID 38441732, 2024). "The expression of NUSAP1 was significantly higher in liver cancer tissues than that in normal tissues and associated with tumor staging I-III but not stage IV." (PMID 35431924, 2022). "Besides modulating the cell cycle to promote the proliferation of liver cancer cells, NUSAP1 can also enhance the cancer stemness characteristics of HCC cells and increase the early recurrence of HCC." (PMID 40535133, 2025). "High expression of NUSAP1 served as an independent predictor for poor prognosis of liver cancers." (PMID 38441732, 2024). "In liver cancer, knockdown of NUSAP1 could inhibit HCC cell proliferation, migration, and invasion in vitro and reduce its growth in vivo." (PMID 35431924, 2022). "Similarly, protein levels of NUSAP1 in liver normal cell HL-7702, liver cancer cell MHCC-97H and NAFLD mice liver significantly elevated." (PMID 35431924, 2022). "The top modular genes, TOP2A, CDC20, PRC1, CCNB2, and NUSAP1, were highly associated with HCC onset and development; high expression of TOP2A, CDC20, or CCNB2 was correlated with poor survival time in TCGA liver cancer patients, implying their potential as biopsy-based prognostic markers." (PMID 31001331, 2019). "The aberrant level of NUSAP1 expression may contribute to the spread of liver cancer." (PMID 39911278, 2025). "Furthermore, knockdown of NUSAP1 inhibited the malignant biological behavior of liver cancer cells." (PMID 38441732, 2024). "In our study, we also demonstrated that NUSAP1 was high up-regulated in NAFLD patients and liver cancer cells under high fat conditions." (PMID 35431924, 2022). "NUSAP1 may play a role in the progression from HBV infection to liver cirrhosis, ultimately leading to liver cancer." (PMID 38441732, 2024). "However, limited information is available regarding the expression and mechanism of NUSAP1 in HBV infection and liver cancer." (PMID 38441732, 2024).
colorectal cancer (10 papers, 2019 to 2025). A primary or metastatic malignant neoplasm that affects the colon or rectum. "For example, the nucleolar and spindle-associated protein 1 (NUSAP1) promotes cell migration and invasion of prostate and colorectal cancer cells." (PMID 38753413, 2024). "In colorectal cancer, NUSAP1 is an independent prognostic biomarker and its depletion induced cell apoptosis, and inhibited cell migration, cell invasion, cell proliferation, and EMT by inhibiting the expression of DNA methyltransferase 1 (DNMT1)." (PMID 30678687, 2019). "NUSAP1 silencing inhibited DNMT1 expression, leading to the inhibition of liver and colorectal cancer progression." (PMID 35739489, 2022). "NUSAP1 gene silencing induced cell apoptosis and inhibited cell proliferation, cell migration, cell invasion, and EMT in colorectal cancer by inhibiting DNMT1 gene expression." (PMID 32153633, 2020).
gastric cancer (10 papers, 2020 to 2025). A primary or metastatic malignant neoplasm involving the stomach. "Our study identifies NUSAP1, a nucleolar and spindle-associated protein, as a key driver of 5-FU resistance in gastric cancer." (PMID 40393971, 2025). "Additionally, data from the GEO database (GSE171054) indicated that NUSAP1 expression was upregulated in 5-FU-resistant gastric cancer patients and that its high expression was associated with poor prognosis in these patients." (PMID 40393971, 2025). "Our previous studies have shown that PRMT1 and PRMT4/CARM1 promote gastric cancer proliferation and metastasis, underscoring the significance of NUSAP1 interactions with PRMT1 and PRMT5." (PMID 40393971, 2025). "In summary, our results demonstrate that NUSAP1 is essential for the proliferation and tumor growth of 5-FU-resistant gastric cancer cells." (PMID 40393971, 2025). "The results revealed that the migration and invasion capacities of NUSAP1-silenced 5-FU-resistant gastric cancer cells were significantly decreased." (PMID 40393971, 2025). "Through proteomic analysis combined with in vitro and in vivo experiments, we found that NUSAP1 is highly expressed in 5-FU-resistant gastric cancer cells, enhancing their resistance to 5-FU and promoting their proliferation, migration, and tumor growth." (PMID 40393971, 2025). "In summary, we found that NUSAP1 is not only upregulated in 5-FU-resistant gastric cancer cells but also enhances cellular resistance to 5-FU." (PMID 40393971, 2025). "Our findings provide preliminary evidence supporting NUSAP1 and its R422 methylation as potential biomarkers for predicting poor prognosis and resistance to 5-FU therapy in gastric cancer patients." (PMID 40393971, 2025). "In conclusion, our study identifies a novel mechanism by which PRMT1-mediated methylation of NUSAP1 promotes 5-FU resistance in gastric cancer by stabilizing Notch2." (PMID 40393971, 2025). "Proteomic analyses of 5-FU-resistant gastric cancer cell lines revealed that NUSAP1 is significantly upregulated, and functional studies demonstrated its essential role in promoting resistance, proliferation, migration, invasion, and tumor growth." (PMID 40393971, 2025). "To rule out interference from the MYC tag, we performed Co-immunoprecipitation (Co-IP) experiments using an anti-NUSAP1 antibody in 5-FU-resistant gastric cancer cells." (PMID 40393971, 2025). "The NUSAP1-Notch2 axis represents a promising therapeutic target for overcoming chemoresistance in gastric cancer." (PMID 40393971, 2025). "In summary, we found that the R422 site of NUSAP1 is critical for promoting 5-FU resistance, cell proliferation, migration, invasion, and tumor growth in gastric cancer 5-FU-resistant cells." (PMID 40393971, 2025). "In other types of cancer, gastric cancer for example, low NUSAP1 expression is proven to inhibit mTORC1 pathway, hence suppressing proliferation, migration, and invasion of cancer cells." (PMID 36258196, 2022). "There have also been studies demonstrating that downregulation of NUSAP1 suppresses cell proliferation, migration, and invasion via inhibition of the mTORC1 signaling pathway in gastric cancer." (PMID 35515139, 2022). "To explore whether NUSAP1 affects other physiological properties of 5-FU-resistant gastric cancer cells, we examined the impact of NUSAP1 knockdown." (PMID 40393971, 2025). "However, NUSAP1 was demonstrated to facilitate cell proliferation, migration, and invasion via inhibition of the mTORC1 signaling pathway in gastric cancer, which was contrary to our results." (PMID 35515139, 2022). "Moreover, analysis of NUSAP1 expression from data deposited from the Oncomine database also revealed that the mRNA expression of NUSAP1 was upregulated in gastric cancer tissues." (PMID 33489890, 2020). "Interestingly, the analysis of these prognostic outcomes indicated that NUSAP1 could be a protective factor for gastric cancer." (PMID 37781040, 2023).
gastric cancer (continued). "BIRC5, CLDN1, DDX58, IL18, NPC2, NUSAP1, and PHC3 were found to have higher expression in gastric cancer tissues compared to normal tissues, and their expression was also elevated in various other cancer types." (PMID 40393971, 2025). "We further identified multiple arginine methylation sites on NUSAP1 and demonstrated that PRMT1-mediated R422me2 modification facilitates its interaction with Notch2, stabilizing Notch2 protein expression and promoting 5-FU resistance in gastric cancer cells." (PMID 40393971, 2025). "Furthermore, NUSAP1 suppresses ubiquitin-mediated degradation of YAP1 and ANXA2, driving gastric cancer progression." (PMID 40393971, 2025).
melanoma (10 papers, 2007 to 2023). A malignant, usually aggressive tumor composed of atypical, neoplastic melanocytes. "The higher expression of NUSAP1 is mainly associated with the poor prognosis of melanoma and breast-invasive carcinoma." (PMID 37304238, 2023). "Notably, patients with melanoma, lung, and kidney cancer with high NUSAP1 expression levels have shorter survival times and lower immunotherapy response rates." (PMID 37781040, 2023). "Interestingly, NUSAP1 was found to be up-regulated in melanoma cells by gene expression profiling of a series of melanoma cell lines." (PMID 21314937, 2011). "For instance, UMAP plots revealed the expression of NUSAP1 in CD4+T, CD8+T, NK, B, DC, monocyte, and macrophage in melanoma (SKCM_GSE120575), with particularly high expression observed in proliferating T cell (T-proli) (the lower plot)." (PMID 37781040, 2023).
astrocytoma (9 papers, 2017 to 2024). "To investigate the association between NUSAP1 and clinical characteristics of the patients, we examined NUSAP1 expression by immunohistochemical analysis of 221 paraffin-embedded astrocytoma tissues." (PMID 28899410, 2017). "Nucleolar and spindle associated protein 1 (NUSAP1) was observed in several types of cancers, but its role in astrocytoma remained unknown." (PMID 28899410, 2017). "NUSAP1 expression can also lead to increased invasion of astrocytoma cells by activating the Hedgehog signaling pathway." (PMID 38441732, 2024). "NUSAP1 can enhance the aggressiveness of tumor cells and participate in the astrocytoma progression by activating the Hedgehog signaling pathway." (PMID 35487972, 2022). "This study revealed that NUSAP1 plays a significant role in promoting aggressiveness in astrocytoma." (PMID 28899410, 2017). "Similar to these findings in various tumors, in this study too, we found that NUSAP1 was dramatically overexpressed in advanced stage astrocytoma patients; moreover, overexpression of NUSAP1 was also predictive of poor overall survival." (PMID 28899410, 2017). "We also found that the NUSAP1-transduced astrocytoma cells displayed an increase in migration ability, while the NUSAP1-silenced cells displayed a decrease in their migration ability in the wound healing assay." (PMID 28899410, 2017). "Our findings indicated that NUSAP1 activated HH pathway by promoting GLI1 transport to the nucleus form cytoplasm in astrocytoma cell." (PMID 28899410, 2017). "The effect of NUSAP1 on proliferation of astrocytoma cells was evaluated by overexpression and silencing of NUSAP1 transcripts." (PMID 28899410, 2017). "Compared with the NHA cell line, the expression of NUSAP1 was also upregulated in all seven astrocytoma cell lines, as confirmed by RT-PCR analyses and western blotting." (PMID 28899410, 2017). "NUSAP1 was markedly overexpressed in astrocytoma cell lines and tissues compared with normal astrocytes and brain tissues." (PMID 28899410, 2017). "In an effort to understand the role of NUSAP1 in astrocytoma, the present study investigates the expression of NUSAP1 in astrocytoma cell lines and tissues." (PMID 28899410, 2017). "Collectively, these data indicated that overexpression of NUSAP1 promoted aggressiveness in astrocytoma." (PMID 28899410, 2017). "Further, analysis of NUSAP1 expression from data deposited in The Cancer Genome Atlas (TCGA) database revealed that the increase in the mRNA expression of NUSAP1 in astrocytoma tissues was in tandem with the increase in the WHO grade of the tumor." (PMID 28899410, 2017). "NUSAP1 was found to be overexpressed in 152 of 221 (68.78%) astrocytoma tissues, and was significantly correlated to poor survival." (PMID 28899410, 2017). "Two hundred and twenty-one astrocytoma tissue samples were analyzed by immunochemistry to demonstrate the correlation between the NUSAP1 expression and clinicopathological characteristics." (PMID 28899410, 2017). "We found that NUSAP1 expression was significantly upregulated in astrocytoma cell lines and tissues compared with normal astrocytes and brain tissues." (PMID 28899410, 2017). "Real-time PCR and western blotting analyses revealed that the mRNA and protein expression of NUSAP1 was higher in the eight astrocytoma tissues than in the two normal brain tissues." (PMID 28899410, 2017). "The expression of NUSAP1 in astrocytoma cell lines and tissues were measured with western blotting and Real-Time PCR." (PMID 28899410, 2017). "An intracranial brain xenograft tumor model was used to confirm the oncogenic role of NUSAP1 in human astrocytoma." (PMID 28899410, 2017). "3-(4,5-dimethylthiazol-2-yl) 2,5-diphenyltetrazolium bromide (MTT) assay, colony formation, transwell matrix penetration assay, wound healing assay and anchorage-independent growth assay were used to investigate the biological effect of NUSAP1 in astrocytoma." (PMID 28899410, 2017).